MIR3662 (microRNA 3662)
Synonyms: hsa-mir-3662; mir-3662
Gene: MicroRNA gene on chromosome 6 (134,979,338 to 134,979,432, reverse strand). Ensembl gene ENSG00000283409.
Homologues: Orthologues: macaque MIR3662 (100% identical).